NEDD8 (NEDD8 ubiquitin like modifier)
Diseases named in the same sentence as NEDD8 in open-access papers (continued):
Sharing a sentence is not in itself a finding about the gene and the disease.
liver fibrosis (2 papers, 2019 to 2023). "In view of the overactivation of neddylation pathway that has been described during liver fibrosis, we were inspired to explore whether EphB1 could be conjugated to NEDD8 in HSCs." (PMID 36834826, 2023).
malaria (2 papers, 2018 to 2020). Malaria is a serious and sometimes fatal disease caused by a parasite that commonly infects a certain type of mosquito which feeds on humans. "We report that malaria parasites encode a NEDD8 protein with or without a C-terminal tail beyond the Gly76." (PMID 33214620, 2020). "Therefore, TCR stimuli could induce Uba3 up-regulation and NEDD8 modification of target proteins, and that P. yoelii 17XNL-driven neddylation might allude to a potential role for this pathway in T cell-mediated defense against blood-stage malaria." (PMID 30462731, 2018). "Most of our knowledge on NEDD8 comes from higher eukaryotes and S. cerevisiae, whereas the NEDD8 of eukaryotic pathogens like malaria parasites has not been characterized yet." (PMID 33214620, 2020).
multiple myeloma (2 papers, 2013 to 2023). "In summary, we provide strong evidence that a novel multiple myeloma-related protein, Myeov2, regulates Nedd8 modification and nucleolar integrity." (PMID 23776465, 2013). "Thus, our findings provide a clue that links Nedd8 pathway to pathogenesis of multiple myeloma." (PMID 23776465, 2013).
pancreatic cancer (2 papers, 2021 to 2022). "Ubc12, Rbx1, and NEDD8 mRNA expression in pancreatic cancer tissues was notably higher than that in normal pancreatic tissues (p < 0.05)." (PMID 35155257, 2022). "In the colony formation assay, NEDD8 knockdown showed an apparent suppressive effect on these two pancreatic cancer cell lines." (PMID 35155257, 2022). "Moreover, correlation analysis revealed that the mRNA levels of NEDD8 and NAE1, Ubc12, and Rbx1 had a statistically significant association with pancreatic cancer." (PMID 35155257, 2022).
psoriasis (2 papers, 2009 to 2023). An autoimmune condition characterized by red, well-delineated plaques with silvery scales that are usually on the extensor surfaces and scalp. "Our GNN also succeeds in separating 83 healthy skin samples from 95 lesional psoriasis samples, revealing that upregulation of 26S- and NUB1-mediated degradation of NEDD8, UBD, and their conjugates is central to the largest perturbed reaction network component in psoriasis." (PMID 37521042, 2023).
squamous carcinoma (2 papers, 2016 to 2019). "Moreover, ILF3 overexpression in adenocarcinoma, and PCNA and NEDD8 in squamous carcinoma shows them as promising candidates for therapeutic purposes." (PMID 27814385, 2016).
atherosclerosis (1 paper, 2021). A disease characterized by the build-up of fatty material and calcium deposition in the arterial wall resulting in partial or complete occlusion of the arterial lumen. "Further, blocking HDAC6 activity directly with tubacin or indirectly by blocking its post-translational modifier NEDD8 with MLN4924, provides options for new therapeutic strategies to treat or reverse endothelial dysfunction and atherosclerosis." (PMID 34220539, 2021).
chronic kidney disease (1 paper, 2025). Impairment of the renal function secondary to chronic kidney damage persisting for three or more months. "We here demonstrated that two key components of the neddylation pathway—NEDD8-activating enzyme E1 subunit 1 (NAE1) and NEDD8—are significantly upregulated in human chronic kidney disease (CKD) specimens compared to healthy kidneys, implicating neddylation in CKD-associated fibrosis." (PMID 39900822, 2025).
chronic viral hepatitis C (1 paper, 2022). "Importantly, NEDD8 levels were not modulated in chronic viral hepatitis C or SLE, suggesting a specific acute response in COVID-19 patients." (PMID 35831294, 2022).
colon cancer (1 paper, 2024). "Together, these data show that the loss of NEDD8 reduces the postoperative lung metastasis of colon cancer cells in mice and imply the participants of NEDD8 in stress-facilitated cancer metastasis via regulating Tregs." (PMID 38177106, 2024). "Depletion of NEDD8 significantly ameliorated the postoperative lung metastasis of colon cancer cells in mice." (PMID 38177106, 2024). "More importantly, the impaired cytotoxic activity of CD8+T cells and NK cells against colon cancer cells after laparotomy surgery was recovered by NEDD8 depletion." (PMID 38177106, 2024). "Postoperative lung metastasis of colon cancer cells was compared between wild-type and NEDD8 knock out mice." (PMID 38177106, 2024). "As measured by cytotoxicity assay, CD8+T cells, and NK cells presented better anti-tumor cytotoxicity against colon cancer cells after co-culturing with Tregs of NEDD8 knock out mice, compared to those of wild-type mice." (PMID 38177106, 2024). "NEDD8 depletion abrogates postoperative lung metastasis of colon cancer cells by inhibiting Treg immunosuppression and thereby partially recovering CD8+T cell and NK cell-mediated anti-tumor immunity." (PMID 38177106, 2024). "In the present study, we, for the first time, identify NEDD8 as a major driver of Treg suppressive function in the context of surgical stress, and disclose the therapeutic potential of NEDD8 blockade to ameliorate surgical stress-facilitated lung metastasis in mice with colon cancer." (PMID 38177106, 2024). "In conclusion, by exploring the role and mechanisms underline Tregs functional alterations upon surgical stress, we demonstrate that surgical stress upregulated NEDD8 expression is essential for the immunosuppressive function of Tregs and contributes to the metastasis of colon cancer in mice." (PMID 38177106, 2024).
COVID-19 (1 paper, 2022). A disease caused by infection with severe acute respiratory syndrome coronavirus 2. "Indeed, we show that serum NEDD8 levels are significantly augmented and specifically associated with COVID-19 patients during the early response to the infection." (PMID 35831294, 2022). "Thus, augmented serum NEDD8 levels were associated with an active immune response against SARS-CoV-2 infection in COVID-19 patients." (PMID 35831294, 2022). "Analysis of ratio final vs initial serum NEDD8 levels showed an increased ratio in severe COVID-19 patients." (PMID 35831294, 2022). "In this study, we show for the first time that patients with active COVID-19 have significantly increased serum NEDD8 protein levels, which are, indeed, positively correlated with serum IgM levels." (PMID 35831294, 2022). "Indeed, inhibition of NAE-1 by MLN4924 resulted in a more significant response in intracellular NEDD8 levels and neddylated secretome analyzed by both western blot and ELISA in COVID-19 patients than in samples from healthy individuals." (PMID 35831294, 2022). "Thus, we evaluated if levels of serum NEDD8 proteins were differentially modulated in COVID-19 patients." (PMID 35831294, 2022).
cystic fibrosis (1 paper, 2024). Autosomal recessive disorder caused by pathogenic variants in the CFTR gene (cystic fibrosis transmembrane conductance regulator), which encodes a chloride and bicarbonate channel expressed in epithelial cells, and follow the diagnosis criteria. "In addition, knockout of the ubiquitin ligase SYVN1 or NEDD8 partially restores ΔF508-CFTR-mediated Cl-transport in human cystic fibrosis airway epithelia, indicating the important role of NEDD8 in ΔF508-CFTR-induced cystic fibrosis." (PMID 39697538, 2024).
E. coli infection (1 paper, 2025). "Consistent with our previous study, E. coli infection also increased neddylation activation, as evidenced by increased protein expression of NEDD8-Cullins in the liver, lung, and kidney of mice." (PMID 39675717, 2025).
endothelial dysfunction (1 paper, 2021). In vascular diseases, endothelial dysfunction is a systemic pathological state of the endothelium (the inner lining of blood vessels) and can be broadly defined as an imbalance between vasodilating and vasoconstricting substances produced by (or acting on) the endothelium. "It would be interesting to know whether mutation of the NEDD8 conjugation site in mice and in cultured HAECs using CRISPR/Cas9 would provide protection against endothelial dysfunction and atherogenesis." (PMID 34220539, 2021).
esophageal carcinoma (1 paper, 2021). A primary or metastatic malignant neoplasm involving the esophagus. "The NEDD8 mRNA expression in 2 histologic subtypes of esophageal carcinoma was significantly higher than that in normal tissues (normal vs. EAC: P = 1.5926E-05; normal vs. ESCC: P = 3.3506E-09)." (PMID 33733647, 2021). "To evaluate the clinical relevance of NEDD8 expression in esophageal carcinoma, we used the TCGA database to determine the levels of NEDD8 transcripts in esophageal carcinoma." (PMID 33733647, 2021).
head and neck cancer (1 paper, 2023). A primary or metastatic malignant neoplasm affecting the head and neck. "Here, we found that NEDD8 upregulation is extensively found in primary tumors compared to normal tissues derived from patients with head and neck cancer and highly correlated with poor responsiveness to radiotherapy in OSCC patients." (PMID 36890567, 2023). "Moreover, targeting NEDD8-related PTMs has also been reported to enhance cellular sensitivity to ionizing radiation in hormone-resistant prostate, pancreatic and head and neck cancers." (PMID 36890567, 2023).
influenza (1 paper, 2013). An acute viral infection of the respiratory tract, occurring in isolated cases, in epidemics, or in pandemics; it is caused by serologically different strains of viruses (influenzaviruses) designated A, B, and C, has a 3-day incubation period, and usually lasts for 3 to 10 days. "Expression of NEDD8 was increased in influenza infected cells suggesting a defense mechanism." (PMID 24116168, 2013).
liver cirrhosis (1 paper, 2015). "Importantly, in a prospective study of patients with liver cirrhosis on ultrasound surveillance at first diagnosis of HCC, global neddylation at protein level as well as Nedd8 and NAE1 gene expression levels were significantly higher in HCC patients with poor prognosis." (PMID 25650664, 2015).
meningioma (1 paper, 2020). A generally slow growing tumor attached to the dura mater. "To inhibit CRL4-DCAF1, we treated meningioma cells with MLN3651, and showed that NEDD8-conjugates were significantly reduced with treatment." (PMID 32629964, 2020).
mental retardation (1 paper, 2010). "Furthermore, p21Cip1-activated kinase 3 (Pak3), which is associated with non-syndromic mental retardation in humans, and Musk, a receptor tyrosine kinase that plays a role in neuromuscular junction organization, were found to be covalently conjugated to NEDD8 in vivo." (PMID 20596523, 2010).
neuroblastoma (1 paper, 2021). Neuroblastoma (NB) is the most common solid, extracranial childhood tumor. "Pevonedistat-induced NEDD8 inhibition would provide an exciting new mechanism to target neuroblastoma." (PMID 34207315, 2021). "Prior work has shown that patients with neuroblastomas with high NEDD8 gene expression have a significantly decreased relapse-free survival compared to patients without elevated NEDD8 expression." (PMID 34207315, 2021).
oral cancer (1 paper, 2023). "We next examined the association between NEDD8 expression and radiosensitivity in a panel of oral cancer cell lines." (PMID 36890567, 2023). "To ascertain the possible mechanism by which NEDD8 upregulation promotes radioresistance in oral cancer, we performed computational simulation using Gene Set Enrichment Analysis (GSEA) software against the gene signatures for NEDD8." (PMID 36890567, 2023). "The correlation between NEDD8 expression and cell viability postexposure to 4 Gy irradiation in the detected oral cancer cell lines was positively correlated." (PMID 36890567, 2023). "Accordingly, RT‒PCR results showed that NEDD8 is highly expressed by primary tumors compared to normal adjacent tissues derived from the oral cancer biobank of Taipei Medical University." (PMID 36890567, 2023). "To understand the correlation of NEDD8 expression with radiosensitivity in oral cancer patients, we performed Pearson’s correlation tests for NEDD8 expression and time to new tumor event or overall survival time in oral cancer patients who were recorded to receive radiotherapy." (PMID 36890567, 2023). "Similar views were also found in GSEA simulation against NEDD8 gene signatures from primary tumors of radiotherapy-receiving oral cancer patients who were stratified as low NEDD8 expression/alive and high NEDD8 expression/dead with disease in Kaplan‒Meier analysis using the GSE42743 dataset." (PMID 36890567, 2023). "Because the Akt/mTOR pathway is known to negatively regulate autophagosome formation, we next examined the correlation of NEDD8 expression with the protein levels of autophagosome components, e.g., Beclin-1, Atg5 and LC3-I/II, in oral cancer cells." (PMID 36890567, 2023). "Notably, HSC3 cells overexpressing constitutively active NEDD8 showed a poorer irradiation response than wild-type NEDD8-overexpressing HSC3 cell variants, implying the involvement of its enzymatic modification, neddylation, toward target proteins in radioresistance in oral cancer." (PMID 36890567, 2023). "We found that the mRNA levels of NEDD8 in primary tumors were significantly (p = 0.022) higher than those in normal tissues from TCGA oral cancer patients but not nonoral cancer patients." (PMID 36890567, 2023). "The data showed that NEDD8 mRNA levels significantly (p < 0.05) and negatively correlated with time to new tumor event in the TCGA HNSCC cohort with irradiation treatment and overall survival time in GSE42743 oral cancer patients receiving radiotherapy." (PMID 36890567, 2023). "By using The Cancer Genome Atlas (TCGA) HNSCC database, we performed transcriptional profiling of NEDD8 in normal tissues and primary tumors derived from nonoral and oral cancer patients." (PMID 36890567, 2023). "Of note, under minimized log-rank p values, we found that the majority (66.3%) of TCGA oral cancer patients, but not nonoral cancer patients, harbored higher NEDD8 expression and had shorter overall and progression-free survival times." (PMID 36890567, 2023). "Kaplan‒Meier analyses using overall and progression-free survival probability for NEDD8 mRNA levels showed that NEDD8 is a poor prognostic biomarker in TCGA nonoral cancer and oral cancer patients." (PMID 36890567, 2023).
osteoporosis (1 paper, 2022). A condition of reduced bone mass, with decreased cortical thickness and a decrease in the number and size of the trabeculae of cancellous bone (but normal chemical composition), resulting in increased fracture incidence. "Neddylation, or the covalent addition of NEDD8 to specific lysine residue of proteins, is a reversible posttranslational modification, which regulates numerous biological functions; however, its involvement and therapeutic significance in osteoporosis remains unknown." (PMID 36289618, 2022).
ovarian carcinoma (1 paper, 2024). A malignant neoplasm originating from the surface ovarian epithelium. "We further investigated the clinical relevance by analyzing the expressions of Insulin, IRS1, IRS2, and NEDD8 in ovarian cancer tissues from patients with or without type 2 diabetes mellitus." (PMID 38272982, 2024). "By conjugating His-tagged-NEDD8 in SKOV3 ovarian cancer cells with and without insulin treatment, we identified differentially expressed proteins (DEPs) in the PC vs His-NEDD8 and PC vs His-NEDD8+insulin comparisons." (PMID 38272982, 2024).
pheochromocytoma (1 paper, 2019). "Other pVHL PTM mutated sites include neddylation upon NEDD8 interaction of Lys159 (RCC and pheochromocytoma), which is required for fibronectin matrix assembly and suppression of tumor development and sumoylation of Lys171 by PIASy, found mutated in RCC." (PMID 30943211, 2019).
renal fibrosis (1 paper, 2025). A final common manifestation of a wide variety of chronic kidney diseases characterized by glomerulosclerosis and tubulointerstitial fibrosis. "NEDD8, a ubiquitin-like protein, covalently binds to substrate proteins, suggesting its involvement in renal fibrosis through protein stabilization." (PMID 39900822, 2025). "Given the marked influence of NEDD8 on RhoA protein stability in renal fibrosis, we investigated its role in the regulation of RhoA protein expression during profibrotic pathogenesis." (PMID 39900822, 2025).
Senile plaques (1 paper, 2015). Senile plaques are extracellular deposits of amyloid in the gray matter of the brain. "However, NEDD8 was additionally found to be present in high amounts in neurofibrillary tangles (NFTs) and senile plaques from a patient with AD, which would suggest that NEDD8 is up-regulated in AD, which we do not see in our iPS-based model." (PMID 25765079, 2015).
steatosis (1 paper, 2020). Increased lipid within the cytoplasm of cells. "Since the cleaved SREBP1c alone is transcriptionally activated, the effect of NEDD8 on the cleavage of SREBP1c might be an important check-point for a better understanding of the SREBP1c-mediated steatosis, which is an open question to date." (PMID 32332706, 2020).
Stroke (1 paper, 2015). Sudden impairment of blood flow to a part of the brain due to occlusion or rupture of an artery to the brain. "In the future, significant proteins including UBC, CUL3, APP, NEDD8, JUP, SIRT7, etc., can be potent drug targets for first aid and emergency treatment within 24 h post-stroke." (PMID 26679092, 2015).
thyroid cancer (1 paper, 2023). "To explore the role of ubiquitin-like proteins (ISG15, ATG8, FAT10, NEDD8, SUMO1, UFM1, URM1 and ATG12) in thyroid cancer, we integrated the datasets (GSE33630, GSE29265 and GSE76039) and analyzed 65 NT, 69 PTC and 40 ATC samples." (PMID 37501099, 2023).
type 2 diabetes mellitus (1 paper, 2024). A type of diabetes mellitus that is characterized by insulin resistance or desensitization and increased blood glucose levels. "The results revealed a contrasting pattern, with reduced NEDD8 expression in patients with type 2 diabetes mellitus, accompanied by an induction of IRS1 and IRS2 expression levels." (PMID 38272982, 2024).